GRP (gastrin releasing peptide)
Diseases named in the same sentence as GRP in open-access papers (continued):
Sharing a sentence is not in itself a finding about the gene and the disease.
encephalitis (1 paper, 2022). An acute inflammatory process affecting the brain parenchyma. "In another study, level of serum pro-gastrin releasing peptide (ProGRP) was higher in anti-GABABR encephalitis patients than in normal population, and the level of serum ProGRP showed significant difference between SCLC and non-SCLC subgroup." (PMID 35515002, 2022).
Ewing sarcoma (1 paper, 2008). A small round cell tumor that lacks morphologic, immunohistochemical, and electron microscopic evidence of neuroectodermal differentiation. "Several deregulated growth factor circuits have been described for Ewing sarcoma cells in the literature such as signaling through the insulin-like growth factor I receptor, by human gastrin-releasing peptide and basic fibroblast growth factor, as well as platelet derived growth factor." (PMID 18177496, 2008).
fungal infection (1 paper, 2023). "Increased GRP expression has been reported in response to abiotic stresses, such as salt, cold, heat, and injury, as well as biotic stress, including fungal infection." (PMID 36769262, 2023).
hyperlipidemia (1 paper, 2022). "Analysis of upregulated DEGs has shown that the following seven genes were common between all complications of TIDM (hyperlipidemia, neuropathy, ketoacidosis, hypothyroidism and PCOS): SPINK9, TRDN, PVRL4, MYO3A, PDLIM1, KIAA1614 and GRP." (PMID 36175575, 2022).
Hypoglycemia (1 paper, 2016). A decreased concentration of glucose in the blood. "Atropine blocks PP release in response to food intake, insulin-induced hypoglycemia, and intravenous infusion of GIP, bombesin, gastrin releasing peptide, neurotensin, and bethanechol." (PMID 27304975, 2016).
Hyponatremia (1 paper, 2025). An abnormally decreased sodium concentration in the blood. "Blood tests revealed hyponatremia (Serum Na 122mEq/L) and a high level of tumor marker (pro-gastrin releasing peptide (GRP) 3666 pg/mL)." (PMID 40125115, 2025). "Blood tests revealed hyponatremia (Serum Na 122mEq/L) and elevated levels of a tumor marker (pro-GRP 3666 pg/mL)." (PMID 40125115, 2025).
influenza (1 paper, 2021). An acute viral infection of the respiratory tract, occurring in isolated cases, in epidemics, or in pandemics; it is caused by serologically different strains of viruses (influenzaviruses) designated A, B, and C, has a 3-day incubation period, and usually lasts for 3 to 10 days. "Taken collectively, the host-derived DAMPs, HMGB1 and GRP, play important roles in mediating influenza-induced disease." (PMID 34282358, 2021).
liver fibrosis (1 paper, 2021). "In our study, we found that the GRP was also satisfactory not only for the diagnosis of liver fibrosis but also for the diagnosis of liver inflammation." (PMID 34522187, 2021).
lung carcinoids (1 paper, 2023). "Several hormones, including serotonin (84%), pancreatic polypeptide, gastrin, gastrin-releasing peptide, calcitonin, ACTH, and growth-hormone-releasing hormone often show positive immunostaining in lung carcinoids; multiple hormones may be found in the same tumor." (PMID 38001701, 2023).
medulloblastoma (1 paper, 2021). A malignant, invasive embryonal neoplasm arising from the cerebellum. "Similar inhibition of viability was seen in DAOY cells when GRP was added to rolipram, as with rolipram alone, showing no growth effects of GRP in this medulloblastoma cell line." (PMID 34539578, 2021).
memory impairment (1 paper, 2018). "The GRPR and its ligand GRP are also implicated in memory impairments in patients with AD, transgenic mouse models of AD, and psychiatric disorders." (PMID 29463009, 2018).
ovarian carcinoma (1 paper, 2000). A malignant neoplasm originating from the surface ovarian epithelium. "Therefore, we investigated the effects of bombesin/gastrin-releasing peptide (GRP) antagonists RC-3940-II and RC-3095 on the growth of human ovarian carcinoma cell line OV-1063, xenografted into nude mice." (PMID 10970693, 2000).
parasitic infection (1 paper, 2011). "GRP has been reported to be down-regulated by parasitic infection in a helminth-mouse system." (PMID 22129081, 2011).
periodontitis (1 paper, 2020). An acute or chronic inflammatory process that affects the tissues that surround and support the teeth. "Our present data suggest that the abnormal GRP in periodontitis-affected ECs is linked to pathological activation of osteoclastogenesis." (PMID 33396360, 2020). "We hypothesized that GRP might be a factor affecting bone loss in periodontitis and set out to investigate changes in GRP expressions in experimental periodontitis models." (PMID 33396360, 2020). "Collectively, analyses on the GRP profiles in periodontitis-affected tissues delineated the abnormal expressions of GRP in epithelial cells (ECs)." (PMID 33396360, 2020). "On the basis of the results of previous experiments, we proceeded to investigate the expression pattern of GRP in mouse and human periodontitis." (PMID 33396360, 2020). "Intriguingly, GRP-positive cells were mostly located at the oral epithelium of samples from experimental periodontitis model." (PMID 33396360, 2020). "Gingival tissue samples from mouse model and patients diagnosed with periodontitis were examined for GRP expression by histological staining." (PMID 33396360, 2020). "Moreover, we established periodontitis model in mouse and obtained patient samples in order to compare the immunostaining of GRP between the oral epithelium of diseased and healthy groups." (PMID 33396360, 2020). "Moreover, ligature-induced periodontitis model in mice and gingival samples from patients with periodontitis displayed increased immunostaining of GRP in the oral epithelium." (PMID 33396360, 2020).
psoriasis (1 paper, 2020). An autoimmune condition characterized by red, well-delineated plaques with silvery scales that are usually on the extensor surfaces and scalp. "The GRP‐GRPR system might be enhanced in the SDH, and itch‐responsive GRPR+ neurons largely contribute to intractable itch in a mouse model of psoriasis." (PMID 32584520, 2020).
sexual dysfunction (1 paper, 2009). Disturbances in sexual desire and the psychophysiologic changes that characterize the sexual response cycle and cause marked distress and interpersonal difficulty. "Taken together, these results suggest that the decline of AR expression in the upper lumbar spinal cord may be a link in the attenuation of the GRP system after SPS exposure, and consequently contributes to the appearance of sexual dysfunctions, including erection and ejaculation difficulties." (PMID 19169356, 2009).
tumor (196 papers, 1994 to 2026). "Elevated levels of gastrin-releasing peptide precursor have been associated with tumor progression and poor prognosis in SCLC." (PMID 41018085, 2025). "Rapid elevation of serum neuron specific enolase (NSE), pro-gastrin-releasing peptidpro-GRP (pro-GRP), and disease stage are recommended as tumor markers and risk factors for early prediction of adenocarcinoma transformation to SCLC." (PMID 40134592, 2025). "In contrast, we found that the sensitivity of three types of biochemical tumor markers associated with SCLC [progastrin-releasing peptide (ProGRP), neuron-specific enolase (NSE), and carcinoembryonic antigen (CEA)] tested before treatment was relatively lower." (PMID 33987084, 2021). "Tumors were clearly visualized at 30 min post injection with an excellent tumor to background contrast as a significant amount of radioactivity was associated with GRP-positive MDA-MB-231 tumor." (PMID 30887136, 2019). "In addition, clinical studies have demonstrated success with radioactive GRP-analogs and GRP-R antagonists for both diagnostic tumor imaging and radiotherapy of GRP-R-overexpressing cancers." (PMID 36525420, 2022). "SHAP analysis highlighted elevated pro-gastrin releasing peptide, tumor volume, red cell distribution width, lactic dehydrogenase, and white blood cell count as risk factors, while dexmedetomidine and higher hemoglobin were protective." (PMID 41517793, 2026). "Longitudinal monitoring of pro-gastrin-releasing peptide (PRO-GRP) levels showed a strong correlation with tumor progression." (PMID 41641108, 2026). "The tumor‐suppressive effect of GRPR antagonists and the growth‐promoting effect of GRP endow them with the dual potential of being both diagnostic markers and therapeutic targets." (PMID 40654157, 2025). "Experimental studies have demonstrated that ProGRP levels represent GRP levels and GRP gene expression, making it a novel tumour marker for SCLC." (PMID 40951894, 2025). "Tumor marker levels showed an elevated progastrin-releasing peptide (ProGRP, 127.28 pg/mL; normal ≤67.42), while neuron-specific enolase (NSE, 15.81 ng/mL; normal ≤16.5) and carcinoembryonic antigen (CEA, 2.90 ng/mL; normal ≤4.5) remained within normal ranges." (PMID 40978039, 2025). "E-cadherin is known to be tumour suppressor in breast and stomach cancers, in which GRP is abundantly produced and activates GRPR." (PMID 40500450, 2025). "After admission, the tumor markers were retested, with a serum pro-GRP level of 100.1 ng/mL, significantly elevated compared to 60.5 ng/mL 1 month ago (reference range: 0–70 ng/mL)." (PMID 41140660, 2025). "GABA has been shown to promote gastrin-releasing peptide secretion in neuroendocrine-like PCa cells, contributing to tumor progression." (PMID 40565311, 2025). "As the disease of NSCLC patients develops, the number of tumor cells increases, and the synthesis and secretion of GRP increase; the expression of serum Pro‐GRP is also upregulated." (PMID 40488279, 2025). "At diagnosis, the patient’s serum tumor markers-pro-gastrin-releasing peptide (pro-GRP) and neuron-specific enolase (NSE)-were elevated at 2,580 pg/mL (normal levels: < 81 pg/mL) and 34 ng/mL (normal levels: < 15 ng/mL), respectively." (PMID 41542009, 2025). "We found the overexpression of the gastrin-releasing peptide in lung ACTH-secreting tumor NET samples compared to all other tumors and normal tissues under analysis." (PMID 40002253, 2025). "At an early stage of tumor development, the growth of androgen-independent PC can be suppressed by the use of RC-160 and the bombesin/gastrin-releasing peptide (GRP) antagonist (RC-3095)." (PMID 38540191, 2024). "Some well-known secreted tumor markers include AFP, cell surface-associated protein (MUC1 or CA15-3), gastrin-releasing peptide, and prostate-specific antigen (or KLK3)." (PMID 35719915, 2022).
tumor (continued). "This publication from 2000 reports a pilot study approved by the Ethical Board of the University Hospital Ghent, assessing the safety, imaging characteristics and efficacy for tumour detection of the GRP analogue 99mTc-RP527 developed for GRP-R scintigraphy." (PMID 35494646, 2022). "According to the results of our study, GRP was also up-regulated in tumor samples compared with normal samples (P = 1.9e−6)." (PMID 35748788, 2022). "Interference of GRP/GRP-R-induced signaling has also been shown to inhibit vascular endothelial growth factor (VEGF)-dependent tumor angiogenesis." (PMID 36525420, 2022). "Among them, TDGF1, and GRP were up-regulated in tumor samples, while NRG1, CRLF1, and IL20RB were down-regulated in tumor samples." (PMID 35748788, 2022). "BN/GRP antagonists, such as RC-3095 and RC-3940-II, have been reported to exert anti-tumor activities in in-vitro and in-vivo mouse xenografts." (PMID 34898475, 2021). "In vivo, GRP tumor growth was faster and maintained the gene signature: ZEB1‐miR200c‐BMI1 axis; high expression of mesenchymal and stem cell‐related factors; and reduced expression of epithelial marker." (PMID 33764690, 2021). "Consistent with the findings of the preclinical study using silibinin, silencing of ZEB1 restored miR‐200c expression in GRP tumor model in our study, along with reduced tumor incidence and slower tumor growth in vivo." (PMID 33764690, 2021). "A recent experiment using a small-molecule inhibitor of GRP found that compound 77427 inhibited tumor cell proliferation in vitro and angiogenesis in vivo." (PMID 34943797, 2021). "In vitro studies (Caco-2 and HT-29 cells) of the mechanisms of tumor cell metastasis showed that GRP promotes tumor cell motility and attachment to ECM, as a result of upregulation of Intercellular Adhesion Molecule-1 (ICAM-1) via FAK." (PMID 32429087, 2020). "GRP is an autocrine growth factor that can stimulate tumor progression in certain cancers when interacting with GRP receptors and are thus a potential target for cancer immunotherapy." (PMID 31906277, 2020). "Laboratory data demonstrated elevated tumor maker level of pro-gastrin-releasing peptide (ProGRP), 4362 pg/mL." (PMID 33352665, 2020). "Motivated by this gap in the inventory of GRPR-directed radioligands we have expanded our research efforts to native human GRP sequences in order to explore their applicability in GRPR-targeted tumor diagnosis and therapy." (PMID 30897789, 2019). "Gastrin-releasing peptide (GRP)-GRP receptor (GRPR) axis can also induce neutrophil migration in the tumor." (PMID 31474975, 2019). "Biodistribution studies of the new analogs, with respect to the GRP-positive tumor xenografted in mice, as well as the scintigraphy studies were performed." (PMID 30887136, 2019). "Firstly, during the initial time intervals (5 min to 60 min p.i.), 99mTc-BN4 and 99mTc-BN3 showed high and significantly higher uptake than 99mTc-BN1, 99mTc-BN2, and 99mTc-BS in the tumor and the GRP-positive tissues, like the pancreas and intestinal tract." (PMID 30887136, 2019). "Receptor affinity, internalization efficiency and tumor uptake of these analogs were favored both by longer peptide chain and by the presence of basic amino acids Lys13 and Arg17 in the native GRP sequence." (PMID 30897789, 2019). "Downregulation of the GRP reduced the numbers of cancer stem cells in vitro and further abolished tumor development in SCID mice." (PMID 31781593, 2019). "BN-peptide-conjugates exhibited high serum stability and significant binding affinity to GRP-positive tumor; rapid internalization/externalization in/from MDA-MB-231 cells were noticed for the BN analogs." (PMID 30887136, 2019). "The mitotic activity of GRP in human tumours is largely mediated by the G-protein-coupled receptor BB2, also known as GRP-receptor (GRPR); interestingly, the interference with GRPR-mediated functions produces significant anti-mitotic effects." (PMID 30543050, 2018).
tumor (continued). "Taken together, these data imply that PKD plays a role in GRP-GRPR induced tumor promotion in HNSCC." (PMID 30419840, 2018). "In a cancer context, selective degradation of angiogenesis regulators such as gastrin-releasing peptide or HIF2α by autophagy affected tumor vasculature and limited tumor growth." (PMID 28459042, 2017). "The apoptosis percentage in the pVIVO1-GFP/VP3 treated tumor was sustained at day-3 and day-25 due to the GRP promoter sustainable effect." (PMID 27411985, 2016). "In spite of recent advances in understanding the role of GRP/GRP-R in tumor progression, signal transduction pathways regulated by GRP and its receptor are not completely understood." (PMID 23468863, 2013). "Gastrin-releasing peptide (GRP) receptors are over-expressed in various human tumor including breast and prostate which can be targeted with bombesin for diagnosis and targeted therapy." (PMID 26224936, 2013). "In the present study, we identify that key oncogenic properties, such as anchorage-independence, migration and angiogenesis, required for tumor invasion and metastasis, were all negatively affected by GRP silencing." (PMID 24039782, 2013). "Pro-GRP is known to be more stable than GRP and is more sensitive and specific tumor marker than NSE in pulmonary SCC and also in extrapulmonary SCC." (PMID 22316327, 2012). "Significant elevations in levels of tumor markers such as pro-gastrin-releasing peptide (ProGRP) or neuron-specific enolase (NSE) are also valuable indicators." (PMID 22638740, 2012). "By activating its receptor (GRPR) located on both tumor and endothelial cells, GRP is also a direct angiogenic factor as shown by in vitro and in vivo angiogenic assays." (PMID 21385454, 2011). "Recently, vaccines targeting GRP displayed an effective anti-tumor response by inducing humoral and cell-mediated immune responses." (PMID 21385454, 2011). "Both bombesin/GRP antagonists significantly decreased the vessel density of the tumours by about 37%, as shown by immunohistochemical detection of vessels on tumour slides." (PMID 14710236, 2004). "Specific high affinity binding sites for BN/GRP were also found on the AN-215-treated tumours (Kd= 5.98±0.91 nM, Bmax=362.6±8.6 fmol mg−1 membrane protein)." (PMID 11953892, 2002). "The presence of high affinity receptors for bombesin (BN)-like peptides on a wide variety of tumours prompted us to employ some of our powerful BN/gastrin releasing peptide (GRP) antagonists as carrier molecules for targeting cytotoxic agents to tumour cells." (PMID 11953892, 2002). "Recently, we developed a series of targeted cytotoxic conjugates based on analogues of peptide hormones such as luteinizing hormone-releasing hormone(LH-RH), somatostatin and BN/GRP, for which high affinity receptors are expressed on a variety of tumours." (PMID 11953892, 2002). "EGF receptors were down-regulated on H69 tumours after treatment with RC-160 and bombesin/GRP antagonists." (PMID 7947094, 1994). "Similarly, pro-GRP has been employed as a tumor biomarker to forecast early histologic changes from NSCLC to SCLC." (PMID 40507907, 2025). "The latest studies have unveiled that GRP may act as an autocrine growth factor for a subgroup of SCLC tumour cells, enabling rapid tumour growth." (PMID 40951894, 2025). "When GRP interacts with its receptor, the biological behaviors of tumor cells are altered, and their proliferation, invasion, and metastasis are intensified, leading to further deterioration of the condition of NSCLC patients, and the prognosis of their survival is greatly deteriorated." (PMID 40488279, 2025). "Moreover, neuron-specific enolase (NSE) and pro-gastrin-releasing peptide (ProGRP) serve as tumor markers." (PMID 38748049, 2024).